LAMP2 (lysosome associated membrane protein 2)
Diseases named in the same sentence as LAMP2 in open-access papers (continued):
Sharing a sentence is not in itself a finding about the gene and the disease.
Danon disease (continued). "Subsequent genetic testing revealed that this patient was hemizygous for a previously unreported deletion mutation (p.Gly221Ilefs∗19) in the LAMP2 gene, confirming the diagnosis of Danon disease." (PMID 33019488, 2020). "Due to the X-linked inherited nature of the LAMP2 gene, male patients with Danon disease usually develop the disease earlier in life (in childhood or adolescence) and display more severe phenotypes than female patients." (PMID 32012649, 2020). "Danon disease is a rare X-linked dominant lysosomal disease, caused by fundamental deficiency of lysosome-associated membrane protein 2 (LAMP2)." (PMID 33023024, 2020). "Danon disease is caused by a deficiency in lysosomal-associated membrane protein-2 (LAMP2), a gene which encodes for a lysosomal membrane protein on chromosome X." (PMID 32012649, 2020). "Danon disease is a severe X-linked disorder caused by deficiency of the lysosome-associated membrane protein-2 (LAMP-2)." (PMID 32751926, 2020). "Danon disease is a rare, severe X-linked disorder caused by deficiency of lysosome-associated membrane protein-2 (LAMP-2) and characterized by skeletal and cardiac myopathy, retinopathy, and intellectual disability." (PMID 32751926, 2020). "Loss of Lamp2 in humans leads to Danon disease, a lysosome and autophagy disorder with cardiomyopathy, skeletal myopathy, and mental retardation." (PMID 32855403, 2020). "Danon disease is a rare X-linked dominant genetic disorder caused by defects in the lysosome-associated membrane protein 2 (LAMP2) gene." (PMID 33019488, 2020). "We obtained blood samples from a male patient suffering from a defect in the LAMP‐2 gene, which is causative for Danon's disease and is associated with defects in autophagy." (PMID 32319705, 2020). "In Danon’s disease, mutations in lysosome-associated membrane protein 2 (LAMP-2) have been identified." (PMID 32998777, 2020). "Only the hiPSC-CM population carrying the mutant LAMP2 allele on the active X chromosome demonstrated the in vitro phenotypes of Danon disease." (PMID 32012649, 2020). "Whole genome sequencing identified a nonsense mutation (codon 520C>T in exon 4) in LAMP2 in a family with Danon disease." (PMID 31277291, 2019). "Danon disease, caused by the mutations in the gene of lysosome‐associated membrane protein 2 (LAMP2,OMIM*309060), is an X‐linked dominant disorder classically characterized by the triad of cardiomyopathy, skeletal myopathy, and intellectual disability." (PMID 30929317, 2019). "Danon disease (OMIM #300257) is an X‐linked dominant genetic condition caused by mutations in the lysosomal‐associated membrane protein 2 (LAMP2) gene leading to a lysosomal disorder." (PMID 30714332, 2019). "We describe identification of a mutation in LAMP2, c.741+1G>T, in a family with Danon disease by whole exome sequencing." (PMID 30714332, 2019). "Ventricular preexcitation was present in 10 (10/197, 5%) unrelated patients with unexplained LVH in whom genetic testing identified three (3/10, 30%) Danon disease patients with different LAMP2 mutations." (PMID 30929317, 2019). "Intracellular vacuoles accumulation with deficiencies of LAMP2 protein was found in both cardiac and skeletal myocytes of patients with Danon disease." (PMID 30929317, 2019). "A 21-year-old female, child of a non-consanguineous marriage, with diagnosisof hypertrophic cardiomyopathy at 18 years of age and with previousdiagnosis of Danon disease, was referred to our service for mutationanalysis of the LAMP2 gene." (PMID 30985853, 2019). "Male predominance typically characterizes Danon disease because of haploinsuffciency of the X‐linked LAMP2 gene, while affected female patients generally have less severe cardiomyopathy and later onset of symptoms." (PMID 30929317, 2019).
Danon disease (continued). "Danon disease is a rare cardiomyopathic disease caused by LAMP-2 deficiency and characterized by the accumulation of glycogen and autophagic vacuoles in cardiac and skeletal muscles, cardiomyopathy, and intellectual dysfunction." (PMID 31277291, 2019). "Genetic mutations in LAMP-2 are known to cause Danon disease, a glycogen storage disorder linked to hypertrophic cardiomyopathy, skeletal muscle weakness, and intellectual disability." (PMID 31277291, 2019). "Three (3/10, 30%) patients with Danon disease were found in association with different mutations in the gene of lysosome‐associated membrane protein 2 (LAMP2)." (PMID 30929317, 2019). "Danon disease is an X-linked cardiomyopathy caused by mutations in the lysosome-associated membrane protein 2 (LAMP2) gene." (PMID 30393632, 2018). "A genetic defect in LAMP2 causes Danon disease (MIM #300257), an X-linked disorder characterized by two cardinal phenotypes of cardiomyopathy and myopathy due to excessive accumulation of autophagic vacuoles (AV) in cardiomyocytes and skeletal myofibers." (PMID 29463847, 2018). "Danon disease (DD) is caused by the absence or malfunction of lysosomal-associated membrane protein 2 (LAMP2)." (PMID 29720683, 2018). "To further investigate the molecular basis for vasculopathy, we analyzed the pathology of the muscular arteries (cerebral, femoral, and coronary arteries) from LAMP-2–deficient mice, which recapitulate the human Danon disease." (PMID 29463847, 2018). "Mutations in the lysosomal LAMP2 gene causes Danon disease which is inherited in an X-linked dominant fashion, eventually developing a hypertrophic cardiomyopathy." (PMID 29576856, 2018). "Danon disease (MIM #300257) is an X-linked dominant cardioskeletal myopathy caused by a primary deficiency of lysosome-associated membrane protein-2 (LAMP-2)." (PMID 30413001, 2018). "PAS-positive vacuoles in lymphocytes have been reported in patients with Pompe’s disease/adult acid maltase deficiency and Danon disease (LAMP2-deficient cardiomyopathy)." (PMID 30591081, 2018). "Danon disease, an X-linked dominant cardioskeletal myopathy, is caused by primary deficiency of lysosome-associated membrane protein-2 (LAMP-2)." (PMID 30413001, 2018). "Earlier studies have demonstrated that of the three LAMP2 isoforms, mutation in LAMP2b was sufficient and important to cause Danon disease." (PMID 29576856, 2018). "We also used B- lymphoblastoid cell lines (B-LCL) derived from a healthy control and Danon disease’s patient, an X-linked human disease caused by mutations in LAMP2 gene.." (PMID 30048497, 2018). "As the proband from the other family had LAMP-2 deficiency in muscle specimens, the family was finally given a diagnosis of Danon disease." (PMID 30413001, 2018). "A genetic LAMP2 defect causes Danon disease, which consists of two major phenotypes of myopathy and cardiomyopathy." (PMID 29463847, 2018). "Danon disease is an X-linked disorder, due to primary deficiency of lysosome-associated membrane protein 2 (LAMP2)." (PMID 29270320, 2017). "The loss of LAMP2 causes a condition called Danon disease that is characterized by thickening of the heart muscle." (PMID 27664420, 2016). "Regardless of the mechanism, our results provide a new insight into the consequences of LAMP-2 deficiency in Danon disease." (PMID 27628032, 2016). "Cells from individuals (Danon disease) and mice with genetic LAMP-2 deficiency have increased numbers of autophagosomes in vivo." (PMID 27628032, 2016). "In humans, mutations in the LAMP2 gene cause Danon disease, an X-linked lysosomal storage disorder characterized by accumulation of vacuolar compartments in heart and skeletal muscle, leading to cardiomyopathy and myopathy." (PMID 27627761, 2016). "Due to the rarity of the disease and the limited access to autopsy brain material, LAMP-2-deficient mice provide an important tool in studying the molecular mechanisms underlying Danon disease neuropathology." (PMID 25637286, 2015).
Danon disease (continued). "Mutations within the Lamp2 gene cause Danon disease, an X-linked “lysosomal glycogen storage disease with normal acid maltase”." (PMID 25637286, 2015). "Neuropathological changes in post-mortem material from a Danon disease patient have been observed which warranted a more in-depth analysis of LAMP-2-deficient murine brain for the presence of neuropathological signs." (PMID 25637286, 2015). "Mutations within the Lamp2 gene cause Danon disease, an X-linked lysosomal storage disorder characterized by (cardio)myopathy and intellectual dysfunction." (PMID 25637286, 2015). "The importance of basal autophagy is highlighted in Danon disease, in which cardioskeletal myopathy arises due to deficiency of LAMP2, a lysosomal membrane protein." (PMID 27551448, 2015). "Danon disease is caused by point loss-of-function mutations in Lamp2 gene leading to lysosomal storage disease." (PMID 23630012, 2013). "It is interesting to note that LAMP2 has been implicated in Danon disease where it caused autophagic vacuolar myopathy in muscles, and retinopathy." (PMID 24066113, 2013). "In humans, a mutated Lamp2 gene results in Danon disease, characterized by intracytoplasmic vacuoles containing autophagic material and glycogen in skeletal and cardiac muscle cells." (PMID 24312444, 2013). "Surviving mice have a phenotype that corresponds to Danon disease, a rare genetic condition caused by LAMP-2 deficiency." (PMID 22809326, 2012). "Danon disease is a rare genetic condition caused by mutations in the X-linked (XL) lysosome-associated membrane protein gene (LAMP2)." (PMID 22290069, 2012). "For example, Danon disease mutations involve the gene encoding lysosome-associated membrane protein 2 (LAMP2), a protein thought to play a role in autophagosome - lysosome fusion." (PMID 22558391, 2012). "LAMP-2 protein deficiency which was detected by immunofluorescence study in striated muscle of the patient supported the diagnosis of Danon disease." (PMID 19402899, 2009). "Mutation on LAMP2 gene, located on chromosome X, than encodes LAMP2 protein was identified as a cause of Danon Disease." (PMID 19402899, 2009). "It is thus well established that different cell types from Danon disease patients that harbor invalidating mutations in LAMP2 exhibit giant lysosomes containing undigested materials characteristic of defects in the fusion of lysosomes with autophagosomes, a feature also found in VEXAS and CHS." (PMID 39865233, 2025). "Interestingly, a WPW pattern was found at the ECG of a cohort of 41 patients with Danon disease, a rare X-linked myopathy caused by a defect in LAMP-2." (PMID 40308332, 2025). "Pompe disease linked to GAA (acid alpha-glucosidase) gene variations, Danon disease associated with LAMP2 (lysosomal associated membrane protein 2) gene variations, and McArdle disease caused by PYGM (muscle glycogen phosphorylase) gene variations all exhibit defective glycogen catabolism." (PMID 40868246, 2025). "Metabolic disorders include Pompe disease (GAA pathogenic variants), characterized by biventricular hypertrophy, hepatosplenomegaly, and hypotonia, and Danon disease (LAMP2 pathogenic variant), presenting in males with concentric LVH, skeletal myopathy, and pre-excitation." (PMID 40868441, 2025). "The postulated pathomechanism underlining Danon disease may be impaired mitochondrial metabolism due to dysfunction of mitophagy, as well as lysosomal and autophagy dysfunction due to LAMP-2 deficiency." (PMID 39456205, 2024). "In fact, Danon disease is also known as “glycogen storage disease due to LAMP2 deficiency”." (PMID 38248465, 2024). "In addition, mice deficient in Lamp2 mimic Danon disease in humans, showing an accumulation of autophagosomes, which severely affects cardiac contractile function." (PMID 38248465, 2024). "In conclusion, we described a de novo LAMP2 mutation in a female with Danon disease." (PMID 37288668, 2023).
Danon disease (continued). "The vast majority of Danon disease cases are due to point mutations in LAMP2 gene." (PMID 37628591, 2023). "Taking into account this and his medical history (the combination of early cardiomyopathy, arrhythmia and conduction abnormalities, and ophthalmic involvement) that implied Danon disease (caused by LAMP2 gene mutation) as the most appropriate diagnosis, we decided to focus on the LAMP2 gene." (PMID 37628591, 2023). "Danon disease, a familial cardiomyopathy associated with impaired autophagy, was modeled using human iPSC-CMs from patients with mutations in the gene encoding lysosomal-associated membrane protein type 2 (LAMP-2)." (PMID 37349842, 2023). "In conclusion, the current study identified a novel de novo mutation of LAMP2 in Danon disease." (PMID 37288668, 2023). "Finally, whole exome sequencing identified a hemizygous stop gain variant in the lysosome-associated membrane protein 2 (LAMP-2) gene, pointing to a diagnosis of Danon disease (DD)." (PMID 37525783, 2023). "In agreement, in both humans and mice, deficiency in lysosome-associated membrane protein-2 (LAMP-2) can result in the spontaneous development of severe cardiomyopathy, referred to as Danon disease, which is accompanied by autophagic vacuolar aggregation and lysosomal function damage." (PMID 34341709, 2021). "A variety of mutations in LAMP-2 have been reported in patients with Danon disease." (PMID 33841177, 2021). "Among these, a particular group of diseases, autophagic vacuolar myopathy, to which Danon’s disease (LAMP2-deficiency) and X-linked myopathy with excessive autophagy (XMEA) belong prominently, feature large autophagosomes in vacuoles similar to our observations." (PMID 34120654, 2021). "The Danon disease caused by loss-of-function of the gene encoding lysosomal associated membrane protein 2 (LAMP2) is a rare X-linked autophagic vacuolar myopathy, which is characterized by multiple system abnormalities, such as heart, skeletal muscle, and liver." (PMID 33935716, 2021). "Danon disease is an X‐linked dominant hereditary condition caused by mutations in the gene encoding lysosomal‐associated membrane protein 2 (LAMP2), leading to failure of lysosome binding to autophagosomes, accumulation of glycogen in the heart, and abnormal cardiac function." (PMID 30714332, 2019). "Danon disease is primarily caused by loss-of-function mutations in the LAMP-2 gene." (PMID 30413001, 2018). "LAMP2 deficiency causes Danon’s disease, an X-linked hypertrophic cardiomyopathy." (PMID 27664420, 2016). "Furthermore, LAMP-2 deficiency in humans leads to Danon disease, which is associated with fatal cardiomyopathy and myopathy." (PMID 25633562, 2015). "Likewise, the neuropathology of LAMP-2-deficient mice and Danon disease patients share common characteristics." (PMID 25637286, 2015). "Similarities in the pathological presentation of Danon disease in cardiac and skeletal muscle of humans and LAMP-2-deficient (LAMP-2-/y) mice that were of a mixed genetic background (SVJ-129/C57BL6-J (Harlan)) highlight the validity of this mouse as a model for the human disease." (PMID 25637286, 2015). "Our data suggest a distinct role of LAMP-2 within the hippocampus that might be causative for the observed intellectual dysfunction in Danon disease patients." (PMID 25637286, 2015). "The phenotypes of the LAMP2-deficient mouse resemble human Danon disease." (PMID 23457579, 2013). "The only known causative gene is Lamp2 whose mutations cause Danon disease." (PMID 23630012, 2013). "The best characterized AVM is Danon disease, in which the causative gene is Lamp2." (PMID 23630012, 2013). "These symptoms mirror those of human Danon disease which is attributed to mutations in LAMP-2." (PMID 18958159, 2008).
Danon disease (continued). "Taylor & Adler (2020) defined that the diagnosis of Danon disease is usually established in a female proband with cardiac preexcitation and cardiomyopathy (either hypertrophic or dilated) by identification of a heterozygous pathogenic mutation in LAMP2 on molecular genetic testing." (PMID 37288668, 2023). "Therefore, we hypothesize that the clinical presentations of Danon disease depend directly on not only LAMP-2 deficiency, but also on the accumulation of autophagic vacuoles." (PMID 30413001, 2018). "Disorders of endolysosomal biogenesis and lysosomal function include primary lysosomal disorders such as LAMP2‐related Danon disease, GBA‐related Gaucher disease, LYST‐related Chediak‐Higashi syndrome, and GAA‐related Pompe disease." (PMID 39420677, 2025). "Less frequent genetic causes are linked to infiltrative or metabolic diseases, such as GLA mutations in Fabry disease, TTR in transthyretin amyloidosis, LAMP2 in Danon disease, and PRKAG2 in glycogen storage cardiomyopathy." (PMID 40868441, 2025). "Genetic testing is especially important for diagnosing syndromic RCM, such as Anderson–Fabry disease (GLA), glycogen storage diseases (PRAKG2), Danon disease (LAMP2), and amyloidosis (TTR), as it allows for cascade testing of family members." (PMID 39685624, 2024). "The diagnosis of Danon disease is confirmed by clinical features and muscle pathology, as well as LAMP-2 deficiency in biopsied muscle and/or western blot analysis, and LAMP2 gene analysis." (PMID 39456205, 2024). "LAMP2 is a component of the lysosomal membrane and its deficiency causes a lysosomal storage disease (LSD) known as Danon disease associated with autophagy deregulation." (PMID 38760822, 2024). "The deficiency of the lysosomal-associated membrane protein-2 (LAMP-2) gene, which encodes for a lysosomal membrane protein on chromosome X, can accordingly cause Danon disease, which often leads to cardiomyopathy and heart failure." (PMID 36658641, 2023). "The first meeting was before and the second meeting was after the identification of LAMP2 gene deletion in Case 1, supporting the diagnosis of Danon disease." (PMID 37628591, 2023). "This study reveals that an Xq24 microdeletion encompassing the entire LAMP2 gene is responsible for the Danon disease." (PMID 37628591, 2023). "In humans, defective autophagy caused by a mutation in the LAMP2 gene (encoding lysosomal-associated membrane protein-2; LAMP-2) leads to Danon disease, manifested by cardiomyopathy and cardiac dysfunction as major symptoms of the disease." (PMID 37623365, 2023). "Although most Danon patients carry mutations that result in a deficiency of all three LAMP2 isoforms, LAMP2B dysfunction is thought to be affected in Danon disease." (PMID 37762105, 2023). "The presence of haploinsufficiency in LAMP2 and the X chromosome inactivation pattern were crucial factors contributing to the early onset of Danon disease in this female patient." (PMID 37288668, 2023). "Among them, LAMP2, GRIA3, PHF6, and HPRT1 genes are associated with Danon disease, Intellectual deficiency, X-linked syndrome, Wu type, BFL syndrome, Lesch Nyhan syndrome and other syndromes." (PMID 38031145, 2023). "In summary: both cases have Danon disease due to LAMP2 gene microdeletion (confirmed by PCR testing (in the father) and CMA studies (in both))." (PMID 37628591, 2023). "In Danon disease, patients either lack or have very low levels of all three LAMP2 isoforms and therefore have defects in both macroautophagy and CMA40." (PMID 35210514, 2022). "Danon disease (DD, MIM # 300257), also termed glycogen storage disease IIb, is a rare X-linked condition caused by deleterious variants in LAMP2 (lysosome-associated membrane protein 2, OMIM # 309060)." (PMID 35200700, 2022). "This uncommon presentation of dilated cardiomyopathy followed by psychiatric impairment, developmental disability, and unique LAMP2 genetic substitution provides a rare phenotype of Danon disease." (PMID 36447708, 2022).